MSH6 (mutS homolog 6)
Diseases named in the same sentence as MSH6 in open-access papers (continued):
Sharing a sentence is not in itself a finding about the gene and the disease.
tumor (continued). "MSH6 and PMS2 are both considered to be tumor-suppressor and mismatch repair (MMR) genes." (PMID 32508881, 2020). "MS-MLPA and MLPA analyses of the normal and tumor samples gave a normal result; there was no observable genomic rearrangement or hypermethylation of MSH6 in this sample." (PMID 32660107, 2020). "We aimed to clarify the effects of MSH6/2 and PD-L1 expression on tumor proliferation and invasiveness in nonfunctioning (NF) PAs." (PMID 32325698, 2020).
tumor (continued). "Selected CRC target genes involved in apoptosis (BAX), tumor growth (TGFβRII), WNT pathway (AXIN2, TCF4, WISP3), DNA repair (ATM, ATR, BLM, BRCA1, BRCA2, DNAPKcs, MBD4, MRE11, MSH3, MSH6, RAD50, XRCC2) and PI3-kinase signaling (PTEN) were analyzed for mutations in MSI-positive HGG samples." (PMID 21637783, 2011). "The MSI-L phenotype has also been related to germline MSH6 mutations, but none of the two MSI-L tumours in this series showed MSH6 mutations or MLH1 promoter hypermethylation." (PMID 16940983, 2006). "Another possibility is that MSH6 inactivation is not at all due to P623L but has been acquired as a somatic event during the development of the tumour." (PMID 15354210, 2004). "Carriers of MSH6 mutations often display late age at onset, carcinomas of the endometrium, and low or no microsatellite instability (MSI) in tumours." (PMID 15354210, 2004). "MSI analysis is not recommended as it may be less sensitive than IHC in ECs especially for the detection of MSH6 deficiency, and BRAF c.1799T>A variants are rare and do not discriminate between LS and sporadic MMR deficient tumours." (PMID 38962168, 2024). "Despite the increased sensitivity of the NCL_MSI assay in the Manchester cohort, it could not reliably identify tumours with inherited pathogenic MMR mutations, particularly cases with isolated MSH6 loss by IHC, classifying six out of eleven as MSS." (PMID 39682157, 2024).
tumor (continued). "CCP deep sequencing outputs detected no change in the coverage of MSH6 exons in the tumor." (PMID 32660107, 2020). "Immunohistochemistry and microsatellite instability analysis were performed in the tumor of the patient, and normal MSH6 expression and no microsatellite instability were observed, thus reducing the likelihood of the variant being associated with an increased risk for OC." (PMID 33008098, 2020). "While there was a rather weak staining difference in the fresh frozen material (the MSH6 antibody is recommended for FFPE tissue by the manufacturer), we observed clearly varying expression patterns of MSH6 in peripheral and rather central areas of the tumor in the FFPE sections." (PMID 28146430, 2017). "In patient 14B-ON3654BD1, carrying a novel missense variant in the MSH6 gene, a normal expression of all MMR proteins was observed in the tumor tissue, indicating that this mutation may not be pathogenic." (PMID 28445943, 2017). "The peripheric portion of the tumor presented a different profile: 5/84 CpG sites were aberrantly methylated, from which 2 sites were shared with the center portion, that is, MSH3 and MLH1, and 3 sites were exclusively methylated in the tumor periphery, that is, MSH6, MGMT, and APC." (PMID 25544907, 2014). "Of the 28 tumours that could be studied, MSI-H was found only in the case with MSH6 deletion." (PMID 16940983, 2006).
tumor (continued). "However, the mutation, P623L, which had no detectable phenotype in our functional assay was found in a patient, whose EC showed high MSI, and MSH6 was the only nonexpressed protein in the tumour among the three proteins tested." (PMID 15354210, 2004). "In addition, in our unselected cohort, many PGVs are identified in genes such as BRCA1, MSH6, PMS2, and NF1, which are crucial not only for germline follow-up but also for selecting appropriate therapies, particularly immune-based or targeted treatments, as observed in other tumor types." (PMID 41168197, 2025). "However, for MSH6 and PMS2 carriers, starting later and extending the intervals between screenings may be more effective considering the balance between cost and timely tumor detection." (PMID 39457591, 2024). "Only one variant in the RB1 and one in the MSH6 genes identified in tissue specimens at low frequency (<5%) were not identified in liquid biopsy samples, and, interestingly one SNV in MTOR gene was identified in liquid biopsy and not in the matched tumor tissue sample." (PMID 34441402, 2021).
tumor (continued). "Study indicates that tumors lacking the mismatch repair protein duo MLH1/PMS2 always have a lower TMB than those tumor lacking a different protein heterodimer, MLH2/MSH6." (PMID 35445008, 2022).